ALCAM (activated leukocyte cell adhesion molecule)
Diseases named in the same sentence as ALCAM in open-access papers (continued):
Sharing a sentence is not in itself a finding about the gene and the disease.
neuroblastoma (10 papers, 2011 to 2025). Neuroblastoma (NB) is the most common solid, extracranial childhood tumor. "In a cohort of 66 infantile neuroblastoma, weak ALCAM staining was linked to a shortened overall survival and recurrence-free survival in the infantile patients." (PMID 34680335, 2021). "Neuroblastoma patients with higher expression levels of ALCAM, CACNA2D3, DST, EPB41L4A or KIF1B had better clinical overall survival in TARGET dataset, GSE49710 dataset and GSE85047 dataset." (PMID 34116676, 2021). "In neuroblastoma, the cellular location of ALCAM seems important because ALCAM on the cellular membrane of neuroblast or missing from the neuropil area of the cells is an indicator for relapse of the patients." (PMID 34680335, 2021). "We found a more favorable outcome for upregulated cell adhesion molecules L1 and ALCAM in pediatric neuroblastoma patients, while higher expression in adult cancer patients was correlated to poor survival." (PMID 31989042, 2019). "Over the past decade, alterations in expression of ALCAM have been reported in several human tumors and recently in renal carcinoma and in neuroblastoma primary tumors." (PMID 21364949, 2011). "However, the low expression of ALCAM indicates poor prognosis in infantile neuroblastoma." (PMID 29375378, 2017). "Meanwhile, three independent neuroblastoma cohorts (Kocak, SEQC, TARGET) consistently revealed significantly elevated expression of NRCAM, VSTM2L, SLIT3, and ALCAM in Stage 4S tumors." (PMID 40448172, 2025). "Therefore, ALCAM could be a potential prognostic marker for neuroblastoma." (PMID 35574403, 2022). "The prognostic effects of age related genes ALCAM, CACNA2D3, DST, EPB41L4A and KIF1B in pediatric neuroblastoma patients were determined by Kaplan-Meier survival." (PMID 34116676, 2021). "Throughout this review, the involvement and effect of these cell adhesion molecules, along with activated leukocyte cell adhesion molecule (ALCAM) and intercellular adhesion molecule 2 (ICAM-2) and potential for therapeutic targets in neuroblastoma is discussed." (PMID 35574403, 2022). "And the higher expression levels of ALCAM, CACNA2D3, DST, EPB41L4A or KIF1B were associated with better prognosis of MYCN non-amplified neuroblastoma patients." (PMID 34116676, 2021). "We found that ALCAM, CACNA2D3, DST, EPB41L4A and KIF1B were associated with the favorable prognosis of MYCN non-amplified neuroblastoma patients." (PMID 34116676, 2021). "Next, we tried to determine the associations of ALCAM, CACNA2D3, DST, EPB41L4A and KIF1B in MYCN non-amplified neuroblastoma patients." (PMID 34116676, 2021). "MYCN non-amplified neuroblastoma patients with lower expression levels of ALCAM, CACNA2D3, DST, EPB41L4A or KIF1B were with lower overall survival in TARGET dataset, GSE49710 dataset and GSE85047 dataset." (PMID 34116676, 2021). "Interestingly, high expression levels of ALCAM, CACNA2D3, DST, EPB41L4A or KIF1B were not only associated with the prognosis of MYCN non-amplified neuroblastoma patients, but also were associated with the prognosis of all neuroblastoma patients." (PMID 34116676, 2021). "MYCN non-amplified neuroblastoma is a heterogeneous disease and could be divided into sub-groups based on age or the expression levels of ALCAM, CACNA2D3, DST, EPB41L4A and KIF1B." (PMID 34116676, 2021). "ALCAM, CACNA2D3, DST, EPB41L4A and KIF1B were highly expressed in MYCN non-amplified younger neuroblastoma patients." (PMID 34116676, 2021). "Furthermore, using multivariate cox regression, we determined the correlations of age, ALCAM, CACNA2D3, DST, EPB41L4A or KIF1B expression in the prediction of the clinical overall survival of MYCN non-amplified neuroblastoma patients." (PMID 34116676, 2021). "Moreover, the prognostic significances of ALCAM, CACNA2D3, EPB41L4A and KIF1B in MYCN non-amplified pediatric neuroblastoma were not previously reported." (PMID 34116676, 2021).
hepatocellular carcinoma (9 papers, 2014 to 2024). A malignant tumor that arises from hepatocytes. "ALCAM is also up-regulated in liver tissue and serum from patients with hepatocellular carcinoma (HCC)." (PMID 36275816, 2022). "In patients with hepatocellular carcinoma, circulating ALCAM was markedly raised compared with controls and, interestingly, much higher than those with patients who carried other malignancies, e.g., breast and other GI cancers." (PMID 34680335, 2021). "MCAM has classically been described in melanoma cells but it also seems to play a role in hepatocellular carcinoma via its interplay with ALCAM which can itself be ubiquitinated (see also Section 4.4)." (PMID 26703751, 2015). "ALCAM and MCAM in combination seem to be promising candidates as diagnostic markers for hepatocellular carcinoma and their crosstalk has intensively been investigated in a hepatocellular carcinoma cell culture model, the Bel-7402 cells." (PMID 26703751, 2015). "Nevertheless, the results showing a tightly regulated expression of MCAM by ALCAM and the ubiquitination of MCAM provides novel and highly interesting insights into the cellular regulation of MCAM and hence into hepatocellular carcinoma and potential future therapeutic approaches." (PMID 26703751, 2015).
lung adenocarcinoma (9 papers, 2015 to 2021). A carcinoma that arises from the lung and is characterized by the presence of malignant glandular epithelial cells. "For example, miR-483-5p has been identified as predictor of poor prognosis in adrenocortical cancer and it has been demonstrated to promote invasion and metastasis of lung adenocarcinoma by targeting RhoGDI1 and ALCAM." (PMID 29149041, 2017). "Focusing on the direct association supported by the literature, the searching results elucidated that for the AC & stage category, only ALCAM, TYR and SART1 are related to lung adenocarcinoma but with very low confidence scores (1.60, 0.25 and 0.25 respectively)." (PMID 30971213, 2019).
adenoma (7 papers, 2011 to 2023). A neoplasm arising from the epithelium. "CD166, another cell adhesion molecule, also known as ALCAM (activated leukocyte cell adhesion molecule), is associated with adenoma to carcinoma development." (PMID 33995625, 2021).
autoimmune disease (7 papers, 2016 to 2025). A disorder resulting from loss of function or tissue destruction of an organ or multiple organs, arising from humoral or cellular immune responses of the individual to their own tissue constituents. "Interestingly, ALCAM (activated leukocyte cell adhesion molecule) has been studied in other autoimmune diseases and has been linked to tissue damage and inflammation." (PMID 39767148, 2024). "CD6 interactions with its ligands—CD166/ALCAM, CD318, and CD44—are important in the pathogenesis of various autoimmune diseases and cancer." (PMID 39996744, 2025). "Sjogren's syndrome and inflammatory bowel disease are two other autoimmune diseases in which CD6 and its ligand ALCAM (CD166) might play an important role in their pathogenesis." (PMID 36275816, 2022).
liver cancer (7 papers, 2016 to 2022). An epithelial or non-epithelial malignant neoplasm that arises from the liver. "For example, microRNA-192, miR-148b-3p, miR-152, and miR-483-5p have been shown to be able to suppress the expression of ALCAM in tumour cells, including gastric, pituitary, and liver cancer cells, possibly by targeting the 3′-UTR binding site of the transcription region of ALCAM gene." (PMID 34680335, 2021).
lupus (7 papers, 2010 to 2025). "Multiple studies now indicate that CD6 and its ligand CD166 (ALCAM) play significant roles in lupus, particularly in its development." (PMID 39996744, 2025). "In the event of lupus inflammation, there is an increase in the release of inflammatory cytokines through this mechanism, accompanied by elevated excretion of ALCAM in urine." (PMID 38915417, 2024). "Similar findings were noted within the spleens of lupus mice, which exhibited enlarged marginal zones with rich cellular expression of ALCAM (CD166), some of which also coexpressed CD11b (costained yellow)." (PMID 34981775, 2022). "Given the increased expression of CD6 and ALCAM in MRL/lpr mice, we evaluated the role of CD6/ALCAM in lupus by blocking the pathway using a mouse CD6-specific monoclonal antibody (anti-CD6)." (PMID 34981775, 2022). "We aim to validate urinary ALCAM as a biomarker in predicting renal disease histpathology in a Chinese lupus cohort." (PMID 32460901, 2020). "ALCAM expression was also up-regulated in the glomeruli and tubules of MRL/lpr lupus-like murine model." (PMID 35720325, 2022). "This study aimed to demonstrate the potential of activated leukocyte cell adhesion molecule (ALCAM), hemopexin (HPX), and peroxiredoxin 6 (PRDX6) as urine biomarkers for systemic lupus erythematosus (SLE)." (PMID 38915417, 2024). "Importantly, urine ALCAM LFA had the capacity to distinguish ALN patients from healthy subjects with high accuracy (ROC AUC=0.93, solid red line) and from all other lupus patients (ROC AUC=0.86, dashed red line), and were very comparable to the performance of the conventional ELISA assay." (PMID 36569940, 2022). "T cells and monocytes isolated from spleens of the lupus mouse strains exhibited similar but smaller increases in both CD6 and ALCAM compared with C567BL/6 mice, suggesting that this pathway may be important both for systemic autoimmunity and end organ disease." (PMID 34981775, 2022).
myeloma (7 papers, 2019 to 2024). "In primary multiple myeloma cells and RPMI8226 cells, ALCAM associates with inactive ligand-free EGFR." (PMID 39594667, 2024). "In myeloma cells, ALCAM is a downstream response protein to migration inhibitory factor (MIF) and an important factor in the interaction between myeloma cells and bone marrow stromal cells." (PMID 34680335, 2021). "EGFR forms a complex with ALCAM in CNE-2R cells and primary multiple myeloma cells and RPMI8226 cells." (PMID 39594667, 2024).
non-small cell lung carcinoma (7 papers, 2012 to 2022). A group of at least three distinct histological types of lung cancer, including non-small cell squamous cell carcinoma, adenocarcinoma, and large cell carcinoma. "Ishiguro and colleagues have stained 147 non-small cell lung cancers and reported that membrane staining is seen in almost half of the tumours and that it is the membrane ALCAM that constitutes a poor prognostic indicator for the overall survival." (PMID 34680335, 2021). "The study has identified that a majority of non-small cell lung cancers (24 out of 25) had a population of cells that were ALCAM-positive but SLC27A2-negative." (PMID 34680335, 2021). "ALCAM has also been evaluated as a prognostic biomarker in a variety of cancers due to its overexpression in patients with breast, ovarian, pancreatic, and non-small-cell lung cancers." (PMID 34641959, 2021). "In the early stages of brain metastasis in non-small cell lung cancer, tumor cells adhere with endothelial cells through VLA-4/VCAM-1, ALCAM/ALCAM, and LFA-1/ICAM-1 binding; these early adhesion molecules can therefore be used as targets to prevent brain metastasis." (PMID 36338717, 2022). "This hypothesis stands in contrast to recent observations by Zhang and colleagues, who identified non small-cell lung cancer (NSCLC) stem cells, or tumor-initiating-cells by ALCAM specific FACS sorting." (PMID 22745698, 2012).
breast tumors (6 papers, 2010 to 2023). "Next, the prognostic value of FN1, PLAU and ALCAM was evaluated in a microarray data set of breast tumors from 2878 patients." (PMID 34641959, 2021). "Wiiger and colleagues have identified a single-chain antibody, scFv173, which recognised ALCAM and was able to reduce ALCAM-mediated cell adhesion and the growth of breast tumours in vivo." (PMID 34680335, 2021). "Immunohistochemical analysis of ALCAM was performed to determine its subcellular localization and level of expresssion in primary breast tumors of AA and CAU women." (PMID 25255861, 2014). "In a comprehensive and classical immunohistochemical analysis of 2197 breast tumours (TMA), Burandt and colleagues analysed the ALCAM staining pattern and found that most tumours stained positive and strong for ALCAM." (PMID 34680335, 2021).
esophageal cancer (6 papers, 2012 to 2021). A primary or metastatic malignant neoplasm involving the esophagus. "An increased levels of s-ALCAM expression was observed in ovarian, breast and esophageal cancer patients compared to healthy controls." (PMID 22745698, 2012).
inflammatory bowel disease (6 papers, 2022 to 2025). A spectrum of small and large bowel inflammatory diseases of unknown etiology. "Similarly, the expression of both CD6 and ALCAM (CD166) is markedly increased in the inflamed mucosa of inflammatory bowel disease patients compared with normal controls." (PMID 36275816, 2022).
lymph node metastasis (6 papers, 2014 to 2023). "Similarly, groups of patients with cytoplasmic/nucleus beta-catenin and cytoplasmic ALCAM staining were also associated with lymph node metastasis and advanced cancer." (PMID 37213285, 2023). "Paradoxically, analysis of 16 cases of lymph node metastases demonstrated a trend correlating shorter CSOS with decreased ALCAM expression (IRS < 8) in metastatic cancer cells." (PMID 26134500, 2015). "Clinico-pathological characteristics including histological type, histological grade, tumor size, lymph node metastasis, estrogen receptor (ER), progesterone receptor (PR), and HER2-neu status were abstracted, and their association with ALCAM expression tested." (PMID 25255861, 2014). "In our opinion the different prognostic significance of ALCAM expression in primary tumor and lymph node metastasis should not be viewed as ALCAM paradox." (PMID 26134500, 2015).
oral cancer (6 papers, 2012 to 2025). "ALCAM is a progression marker of a variety of cancers, including oral cancer and has emerged as an important diagnostic and prognostic marker." (PMID 23840677, 2013). "Correlation of loss of E-cadherin and β-catenin with cytoplasmic ALCAM accumulation both in vitro and in in vivo suggests that these dynamic changes in cell adhesion system may play pivotal role in oral cancer." (PMID 23840677, 2013). "We reported increased expression of ALCAM to be an early event in oral cancer development and its progressive cytoplasmic accumulation correlated with disease progression." (PMID 23840677, 2013). "The effect of siRNA mediated ALCAM knockdown on E-cadherin and β -catenin was determined using western blot, confocal microscopy and RT-PCR analysis in oral cancer cells." (PMID 23840677, 2013).
bladder cancer (5 papers, 2017 to 2021). "However, loss of ALCAM by immunohistochemistry correlates with advanced stage in prostate and bladder cancer, but the loss of ALCAM protein in the tumor tissue is inconsistent with the persistent and sometimes elevated expression of ALCAM mRNA18,19." (PMID 29453336, 2018). "Patients with bladder cancer have been found to have markedly increased levels of soluble ALCAM in the circulation." (PMID 34680335, 2021). "In a comprehensive analysis of ALCAM in bladder cancer tissues, serum, and urine, it was found that ALCAM staining exhibited a progressive decrease with increased tumour stages." (PMID 34680335, 2021). "While both serum and urine soluble ALCAM had a marked increase in patients with bladder cancer, the levels of urinary soluble ALCAM revealed a significant correlation with overall survival and tumour stage." (PMID 34680335, 2021). "This was validated by directly comparing the relative abundance of ALCAM-Iso2 between the GTEx (normal bladder) and TCGA (bladder cancer) cohorts (P = 0.0224)." (PMID 29453336, 2018). "To investigate this further, we evaluated ALCAM expression in both normal bladder and bladder cancer tissue." (PMID 29453336, 2018). "Together, these data indicate that differences in ALCAM isoform expression can be important for bladder cancer progression." (PMID 29453336, 2018). "ALCAM expression in tumor (n = 198) and shedding in biofluids (n = 120) were measured in two separate VUMC bladder cancer cystectomy cohorts by immunofluorescence and enzyme-linked immunosorbent assay, respectively." (PMID 27894096, 2017). "Not only was ALCAM detectable, immunoblots of urine from patients with bladder cancer as well as, from tumor cell lysates and conditioned media, reveal two pieces of evidence verifying biofluid ALCAM is actually proteolytically cleaved, shed ALCAM." (PMID 27894096, 2017). "Analysis of ALCAM mRNA expression was performed on four independent bladder cancer cohorts available as GEO datasets at NCBI (GSE31684, n = 93; GSE48276, n = 126; GSE13507, n = 176; GSE3167, n = 46)." (PMID 27894096, 2017). "ALCAM-Iso2-dominated expression in bladder cancer tissue, compared to normal bladder, further emphasizes that ALCAM alternative splicing may contribute to clinical disease progression." (PMID 29453336, 2018). "Finally, we show a switch from nearly equal isoform expression in normal bladder tissue to ALCAM-Iso2-dominated expression in bladder cancer, which further supports the role of ALCAM-Iso2 in tumor progression." (PMID 29453336, 2018). "The elevated expression of ALCAM-Iso2 observed in the tumor tissue from bladder cancer patients gives further support to the hypothesis that alternative splicing of ALCAM contributes to the progression of cancer." (PMID 29453336, 2018). "In conclusion, shed ALCAM may be a novel prognostic biomarker in bladder cancer, although prospective validation studies are warranted." (PMID 27894096, 2017). "A comparison of non-muscle invasive (NMIBC) and muscle invasive (MIBC) bladder cancer revealed that ALCAM expression is not significantly altered during BCa progression to invasive disease." (PMID 27894096, 2017). "Therefore, ALCAM shedding is not specific to bladder cancer." (PMID 27894096, 2017).
nephritis (5 papers, 2022 to 2025). Inflammation of renal tissue. "In contrast, ALCAM and HPX are associated with nephritis and central nervous system (CNS) involvement." (PMID 38915417, 2024). "In the context of SLE, ALCAM has been found to be upregulated in patients with active disease, particularly in those with nephritis." (PMID 39767148, 2024). "Urinary ALCAM, PF4, and VCAM-1 are potential biomarkers for predicting kidney disease activity in cSLE and hold potential as surrogate markers of nephritis flares in these patients." (PMID 35720325, 2022). "As a next-generation biomarker, urine ALCAM distinguishes active LN from never LN (quiescent or no prior nephritis), previous LN, and controls with high accuracy." (PMID 36569940, 2022). "The next-generation biomarker, urine ALCAM, distinguishes active LN (ALN) from non-active LN (quiescent or no prior nephritis), and previous LN, alluding to its role in renal SLE." (PMID 36569940, 2022).
rectal cancer (5 papers, 2014 to 2026). A primary or metastatic malignant neoplasm that affects the rectum. "In a rectal cancer study containing patients who received 5-FU-based neoadjuvant therapies, it was indicated that those with high pre-therapy ALCAM tumours had a significantly long disease-free survival, independent of other factors." (PMID 34680335, 2021).